DLC1 (DLC1 Rho GTPase activating protein)
Diseases named in the same sentence as DLC1 in open-access papers (continued):
Sharing a sentence is not in itself a finding about the gene and the disease.
tumor (continued). "In another study of HCC samples (100 cases), DLC1 expression was found to be significantly down-regulated, and its low expression may promote tumour invasion and metastasis by disrupting Rho-GTPase activity, thereby affecting the dynamic remodelling of the cytoskeleton." (PMID 40045379, 2025). "Then we tested whether the tumor-promoting effects of miR-186-5p depend on its regulation on DLC1." (PMID 35280693, 2022). "DLC1 might be an attractive target for tumor immunotherapy in EC." (PMID 35223504, 2022). "The RhoGAP domain negatively regulates Rho activity by promoting the conversion of active Rho-GTP to inactive Rho-GDP, which was initially hypothesized to be the sole basis of DLC1’s tumor suppressor functions, by remodeling the cytoskeleton and inhibiting neoplastic growth and cell migration." (PMID 34727930, 2021). "The interaction of DLC1 with Caveolin-1 was found to be essential for DLC1 to inhibit migration and anchorage-independent growth but not to affect the DLC1 RhoGAP activity, representing another example of a RhoGAP-independent mechanism of DLC1 tumor suppressor activities." (PMID 34727930, 2021). "Whether DLC1 is an important target of YAP/TAZ in the tumor endothelium remains to be addressed." (PMID 33614496, 2020). "However, little is known about the function of DLC1 in the progression of spontaneous neoplasms." (PMID 28903430, 2017). "Interestingly, PPARγ has been found to increase Dlc1 expression to inhibit tumor growth, and because PPARγ is a master regulator of adipogenic differentiation, we ask whether PPARγ can also regulate Dlc1 level in adipocytes and affect differentiation." (PMID 28358928, 2017). "This region when mutated does not interfere with Dlc1’s RhoGAP activity, indicating that signalling pathways other than Rho may also be needed for its tumor suppressor activity (ibid)." (PMID 26353792, 2015). "Therefore, the low proliferation rate may be associated with the abundant presence of the tumor suppressor, DLC1 within the tumor microenvironment." (PMID 25013499, 2014). "We recently demonstrated that the transcriptional coactivators MKL1 and 2 mediate the effects of loss of the tumour suppressor DLC1: lack of DLC1 leads to nuclear localization of MKL1/2 in primary human HCC cells, resulting in constitutive activation of several tumour-relevant MKL target genes." (PMID 23853104, 2013). "The results of this study provide conclusive evidence that loss of DLC1, combined with an oncogenic stimulus, promotes HCC in vivo and that this oncogenic process is associated with activation of RhoA, which is a key consequence of loss of DLC1 tumor suppressor activity." (PMID 22580498, 2012). "In order to find out whether methylation of the Dlc1 promoter was responsible for decreased expression of Dlc1 mRNA and protein, we treated the tumour derived cell lines with DNA demethylating agent 5′-azacytidine (5 AzaC) and then studied the expression of Dlc1 mRNA and protein." (PMID 22792269, 2012). "Again, the tumor suppressor function of DLC2 function may be compensated by DLC1." (PMID 19668331, 2009). "Immunoblot analysis of tumor and liver tissue validated an inverse correlation between FLNA pSer2152 and DLC1 expression in tumor versus control tissues." (PMID 41317652, 2026). "Further supporting this tumor-suppressive function, high TNS2 expression in human liver tissue inhibits proliferation and induces apoptosis in HCC cell lines through direct DLC1 interaction." (PMID 40906372, 2025). "The results confirmed DLC1, Caveolin-1 and PLCD1 protein levels were lower in tumor tissue compared to normal adjacent lung." (PMID 34727930, 2021). "Several RhoGAPs, including deleted in liver cancer 1 (DLC1) 6, ARHGAP24 7, ARHGAP26 8, and ARHGAP10 9, appear to function as tumor suppressors." (PMID 33994864, 2021). "miR483-3p was found to target DLC-1, BRCA-1 and PUMA which are a candidate tumor repressor, a tumor repressor and an apoptosis modulator, respectively." (PMID 34593874, 2021).
tumor (continued). "Overall, the interaction between DLC1-START, Caveolin-1, PLCD1, and phosphatidyserine (PS) contributes to DLC1 tumor suppressor function(s) in a RhoGAP-independent manner." (PMID 34727930, 2021). "We find that conserved residues of DLC-1 and DLC-2 START domains are highly overrepresented in tumor samples from a broad spectrum of cancers." (PMID 33142932, 2020). "Using the Catalogue of Somatic Mutations in Cancer (COSMIC) dataset and evolutionary and structure-function analyses, we identify several conserved residues likely to be required for START-directed regulation of DLC-1 and DLC-2 tumor-suppressive capabilities." (PMID 33142932, 2020). "On the side of the DLC-1 signaling, this study reveals for the first time that the DLC-1 tumor suppressor is able to inhibit the immunomodulation of hUC-MSCs." (PMID 33148199, 2020). "In vitro, DLC1 specifically inactivates the small GTPases RhoA, RhoB and RhoC through its GAP domain and this appears to contribute to its tumor suppressor function in vivo." (PMID 29036929, 2017). "DLC1 is a GAP primarily for RhoA and has been mainly studied in cancer research as a tumor suppressor." (PMID 28358928, 2017). "Two other binding partners of Dlc1 that interact through the SAM2 domain are the multifaceted eukaryotic elongation factor 1A1 (EF1A1) and the PTEN tumour suppressor." (PMID 26977077, 2016). "In primary cancers, aberrant DNA methylation has been observed at tumor-suppressor genes, including DAPK1, DLC1, p15, p16, and RASSF1A." (PMID 26823082, 2016). "The DLC1 interactions with talin and FAK contribute to the biological activity of DLC1, including its tumor-suppressor activity, establishing the physiological importance of these interactions." (PMID 27265849, 2016). "In LSC and LAD, DLC1 expression was reduced 24-fold and 10-fold, respectively, while the fold reduction for DLC2 and DLC3 in both of these tumor types was less than one-half as much." (PMID 27174913, 2016). "Four genes, CAMK2N1, CGNL1, DLC1 and SYT11, the expression of which was lower in the tumor tissues than in the normal tissues, were enriched in the cell junction." (PMID 25789025, 2015). "Dlc1 has also been found to bind FAK (focal adhesion kinase) and talin with this binding region being needed for its full tumor suppressor activity in vitro." (PMID 26353792, 2015). "It was shown to interact with RhoGAP DLC1 (Deleted in Liver Cancer 1) via its SH2 domain through an atypical, phospho-tyrosine-independent manner and strongly regulates the localization and tumor suppressive action of DLC1." (PMID 26035355, 2015). "A recent report has suggested that DLC1 binds to FAK and is important for its tumor suppressive function." (PMID 26223867, 2015). "Taken together, our study has shed mechanistic insight into EZH2-H3K27me3 epigenetic repression of DLC1 and advocated the significant pro-metastatic role of EZH2 via repressing tumor and metastasis suppressors." (PMID 23826380, 2013). "We reported DLC1 interaction with S100A10, an inflammatory protein and a key cell surface receptor for plasminogen that regulates pericellular proteolysis and tumor cell invasion." (PMID 22580498, 2012). "Ectopic overexpression of DLC1 in HCC cells expressing oncogenic Ras and containing increased GTP-bound RhoA, abolished the tumor formation." (PMID 22580498, 2012). "As one of the downstream genes of DLC1, FAK can be dephosphorylated on tyr397 and tyr925; the subsequently down-regulated p-FAK Y397 and p-FAK Y925 are able to play important roles in tumor suppression and metastasis suppression." (PMID 22272086, 2011). "Among the genes differentially methylated are number of well- known tumor suppressor genes, namely RASSF1, DLG1, DLC1 and PRDM2, as well as various other tumor related genes." (PMID 24212793, 2011). "There have been several lines of in vitro evidence to support the tumor suppressor role of these two Rho GAP proteins, DLC1 and DLC2." (PMID 19668331, 2009).
tumor (continued). "Similar to its homolog DLC1, DLC2 is underexpressed in human HCCs and has tumor suppressor functions in cultured cells." (PMID 19668331, 2009). "In contrast, SRF inactivation induces apparent senescence in smooth muscle cells and activates oncogene-induced senescence in cancer cells lacking the DLC1 tumour suppressor, a RhoGAP." (PMID 41200793, 2025). "The tumor immunity- and inflammation-related activities, such as Wnt signaling pathway, leukocyte transendothelial migration, and JAK–STAT signaling pathway, were mainly enriched in the high-DLC1 expression group." (PMID 35223504, 2022). "DLC1 levels might be useful in predicting the prognosis of patients with UCEC and especially governing the status of tumor microenvironment transition from immune-dominant to metabolic-dominant." (PMID 35223504, 2022). "Compared with epithelial cells of the non-neoplastic gastric mucosa, DLC1 protein was downregulated in tumour cells (*p < 0.05 vs. NT, Kruskal–Wallis test with Dunn post-tests)." (PMID 35963849, 2022). "In various cancer types, DLC1 was identified as a potential tumor suppressor, however, the effects of DLC1 do not work in only one direction." (PMID 36173625, 2022). "The fact that some of these EV proteins (e.g., PBIP1 and APOC2), mRNAs (e.g., DLC1 and MTO1), and miRNA (e.g., hsa-miR-99a-5p and hsa-mir-203a-3p) are present in the EVs of EC or SI tumor patients, exclusively, suggests that they are able to fulfill that unique role." (PMID 36568159, 2022). "To obtain additional evidence on the role of miR-200c-3p towards DLC1, we investigated further, by transiently transfected miR-200c-3p mimic or inhibitor in HGSC cell lines, which were CAOV3 (primary tumor) and SKOV3 (isolated from ascites), together with their respective negative controls." (PMID 34071861, 2021). "Group-specific distal enhancers or SEs could control TSGs such as DLC1 and MAPK10 directly or indirectly via group-specific core regulators, which might help to explain the downregulation of these TSGs and tumor progression in GII." (PMID 34001209, 2021). "While the DLC-1 gene expresses in almost all normal tissues, it is frequently absent or dramatically down-regulated in tumor tissues mainly due to genomic deletion and/or aberrant methylation at the promoter region of the gene." (PMID 33148199, 2020). "In the annual fish, resveratrol down-regulated acetylation of K-Ras, phosphorylation of FoxO3a, acetylation of FoxO1 and phosphorylation of DLC1 by SIRT1 or SIRT1-mediated inactivation of K-Ras/PI3K/AKT signal, and inhibited cell proliferation and promoted cell apoptosis in spontaneous neoplasms." (PMID 28903430, 2017). "DLC1 expression was significantly lower in HCC tissues than in adjacent noncancerous tissues, and DLC-1 expression was found to be negatively correlated with tumor differentiation, TNM stage and lymph node metastasis." (PMID 26846339, 2016). "Low or no DLC1 protein expression was observed in a large proportion of tumor tissues, in accordance with the mentioned microarray results." (PMID 27614886, 2016). "In addition, the CMIs of CDKN2B, RASSFIA, DLC1 and CCND2 in the OCSPCs from ascites were significantly higher than those in the OCSPCs from tissues (p = 0.001) or bulk tumor cells (p = 0.038)." (PMID 26597084, 2015). "A lack of DLC1 immunoreactivity was observed to localize primarily within the sites of tumor samples that demonstrated diminished reticulin fiber staining." (PMID 25013499, 2014). "The MKL1/2-mediated senescence response has not been noticed before, probably because the tumour cells used in previous studies express DLC1." (PMID 23853104, 2013).
tumor (continued). "In particular, we envisage that MKL1 inhibitors will have enormous as yet unappreciated therapeutic potential to inhibit the growth of tumours lacking DLC1." (PMID 23853104, 2013). "In contrast with the negative effect of interaction with p120RasGAP on DLC1 tumor suppressor function, preliminary evidence indicates that DLC1 interaction with α-catenin enhanced DLC1 anti-oncogenic activity." (PMID 22580498, 2012). "The familial history, age, tumor histology and differentiation did not influence the expression of DLC1 and p-FAK Y397." (PMID 22272086, 2011). "Tumor sections negative for DLC1 exhibited increased FLNA pSer2152 levels." (PMID 41317652, 2026). "The increased EMT plasticity of cells lacking DLC1 may explain its importance as a tumor suppressor." (PMID 40354489, 2025). "However, in both human and mouse, smooth muscle cells that lack SRF exhibit an increased propensity to enter senescence, while MRTF–SRF signalling suppresses oncogene-induced senescence in cancer cells lacking the tumour suppressor DLC1, a RhoGAP." (PMID 41200793, 2025). "Furthermore, mechanism investigation revealed M2-EVs transferring miR-186-5p inhibited DLC1 expression by targeting its 3'UTR, and restored DLC1 successfully neutralized the tumor-promoting effects of M2-EVs transferring miR-186-5p via inhibiting the β-catenin pathway." (PMID 35280693, 2022). "Accordingly, the downregulation of DLC1 with the advancing stage of UCEC and the conversion of TME from immune-predominant into metabolic-dominant status indicated that DLC1 might be a potential tumor suppressor in UCEC." (PMID 35223504, 2022). "DLC1 was not significantly correlated with CDK6 expression when all tumor types were considered (P = 0.0817, correlation = 0.0769) but was significantly positively correlated with CDK6 in ER-positive tumors (P = 2.18E−9, correlation = 0.2967), indicating the involvement of ER in this interaction." (PMID 25425654, 2014). "Since oncogene-induced senescence suppresses tumour growth, we asked whether in DLC1-negative cells MKL1/2 downregulation may substitute for the tumour-suppressive actions of DLC1." (PMID 23853104, 2013). "The interaction of DLC1 with p120RasGAP protein, which is implicated in cross-talk between Ras and Rho, not only provided relevant data for the negative modulation of DLC1 tumor suppressor activity but may, also, lead to potential clinical interventions." (PMID 22580498, 2012). "It is also not known, which Dlc1 isoform is critical for tumour suppression." (PMID 22792269, 2012). "Thus, a talin R8 K1530E/K1544E double mutant markedly reduced binding to DLC1 peptides in vitro, and to full-length DLC1 in cells, compromising the ability of GST-talin R8 constructs to displace DLC1 from endogenous talin and thereby to attenuate the tumor-suppressor activity of DLC1." (PMID 27265849, 2016). "Since tumour suppressors are generally not amenable to direct therapeutic targeting, pharmacologic intervention at the level of MKL1/2 may have broad therapeutic potential in DLC1-deficient cancers." (PMID 23853104, 2013). "DLC1 can be phosphorylated (by PKA, PKB, PKC and PKD) and its phosphorylation has positive or negative effect on its tumor suppressor activity in cancer cells and in nude mice." (PMID 28903430, 2017). "We found a negative correlation between DLC-1 expression and Tumor differentiation (p < 0.001) and TNM stage (p < 0.001).In addition, the expression of DLC-1 in low invasion groups was higher than those in high invasion groups (p < 0.001)." (PMID 26846339, 2016). "In LAD, DLC1 expression, but not DLC2 and DLC3 expression, was higher in the “No New Tumor” group than in the “New Tumor” group." (PMID 27174913, 2016). "DLC1 is not silenced in canine NHL, but the statistically significant relationship with the malignant phenotype suggests that hypermethylation may be used as a biomarker for neoplasia in abnormal lymphoid populations." (PMID 19912643, 2009).
cancer (112 papers, 2007 to 2026). A tumor composed of atypical neoplastic, often pleomorphic cells that invade other tissues. "GMIP belongs to the ARHGAP family of genes, and its family member DLC1 has been reported to be highly associated with cancer." (PMID 40275529, 2025). "According to the Human Protein Atlas, DLC1 is a cancer-related tumor suppressor protein that encodes a GTPase-activating protein (GAP)." (PMID 36984515, 2023). "H. pylori-induced DLC1 loss is an early molecular event, which makes it a potential marker or target for subtype-aware cancer prevention or therapy." (PMID 35963849, 2022). "Two negative controls for the interaction were DLC1 deletion mutant 929–957 and a previously characterized DLC1 cancer-associated point mutant E996K, whose mutation lies just downstream from the amino acids in the deletion mutant." (PMID 34727930, 2021). "A structural model of DLC1-START was also built to better understand the structural implications of the cancer-associated mutations in DLC1-START." (PMID 34727930, 2021). "Rho-GTP, cell proliferation, cell migration, and/or anchorage-independent growth assays were used to investigate the contribution of PS and PLCD1, or the implications of TCGA cancer-associated DLC1-START mutants, to DLC1 functions." (PMID 34727930, 2021). "The analysis of several cancer-associated DLC1-START mutants provides strong evidence for the importance of this domain for DLC1 in tumorigenesis." (PMID 34727930, 2021). "Intriguingly, some of the possible miR-141 targets are associated with cancer metastasis e.g. DLC1, insulin receptor substrate 2 (IRS2) and salt-inducible kinase 1 (SIK1)." (PMID 28095864, 2017). "One identified mechanism for ROCK activation in cancer involves the loss of function of the DLC-1, which encodes a GTPase activating protein (RhoGAP) for the RhoA and RhoC small GTPases." (PMID 26846339, 2016). "This is in agreement with the fact that poorer outcome is associated with the rare allele of DLC1, and DLC1 is frequently lost in cancer." (PMID 25425654, 2014). "Here, loss of RhoGAPs, such as DLC1, is associated with cancer, which suggest that RhoA signaling affects cell fate." (PMID 25211221, 2014). "Despite its significance, there are currently hardly any targeted therapeutic options for cancers caused by loss of DLC1." (PMID 23853104, 2013). "Studies have found that the mRNA levels of DLC1 are diminished in various cancers, including breast, through loss of heterozygosity or heterozygous gene deletions." (PMID 22616718, 2012). "Genes with putative miR-200a targeting sequences that have been implicated in cell migration and cancer include Abelson murine leukemia viral oncogene homolog 2 (Abl2), deleted in liver cancer 1 (Dlc1), Eph receptor A7 (EphA7), and Zeb1." (PMID 20957176, 2010). "The obtained results indicate that FLNA pSer2152 may be a valuable target for the therapy of DLC1-deficient cancers." (PMID 41317652, 2026). "In short, DLC1 deficiency reduces an opportunity for cancers to progress." (PMID 35414117, 2022). "Similarly, our data indicate that some cancer-associated DLC1 START mutants bind PS less efficiently than DLC1 WT, and that they display impaired inhibition of migration and anchorage-independent growth, without affecting DLC1 RhoGAP activity." (PMID 34727930, 2021). "In many cancer cells, the inactivation of RhoGAP caused by DLC1 gene silencing can activate RhoGAP protein, which can continuously transmit growth signals to cells, which may be one of the main mechanisms of tumorigenesis." (PMID 32725802, 2020). "A recent pan-cancer analysis also showed that DLC-1 missense mutations are common in cancer cells." (PMID 33142932, 2020).